FBXL3 (F-box and leucine rich repeat protein 3)
Description:
Substrate-recognition component of the SCF(FBXL3) E3 ubiquitin ligase complex involved in circadian rhythm function. Plays a key role in the maintenance of both the speed and the robustness of the circadian clock oscillation. The SCF(FBXL3) complex mainly acts in the nucleus and mediates ubiquitination and subsequent degradation of CRY1 and CRY2. Activity of the SCF(FBXL3) complex is counteracted by the SCF(FBXL21) complex.
Synonyms: FBL3A; FBXL3A; FBL3; IDDSFAS
Tractability: PROTAC: ubiquitination databases record sites on it.
Gene: Protein-coding gene on chromosome 13 (76,992,598 to 77,027,195, reverse strand). Ensembl gene ENSG00000005812.
Subcellular location: Nucleus; Cytoplasm
Subcellular location (Human Protein Atlas): Nuclear bodies
Pathways (Reactome):
Metabolism of proteins: Association of TriC/CCT with target proteins during biosynthesis; Neddylation
Circadian clock: Degradation of CRY and PER proteins
Immune System: Antigen processing: Ubiquitination & Proteasome degradation
Gene Ontology:
Molecular function: protein binding; ubiquitin-protein transferase activity
Biological process: regulation of circadian rhythm; SCF-dependent proteasomal ubiquitin-dependent protein catabolic process; entrainment of circadian clock by photoperiod; protein destabilization; protein ubiquitination; proteasome-mediated ubiquitin-dependent protein catabolic process
Cellular component: nuclear body; SCF ubiquitin ligase complex; cytosol; nucleus; ubiquitin ligase complex; cytoplasm
Genetic constraint (gnomAD): Loss-of-function variants: 11 observed, 33.37 expected, observed/expected ratio (o/e) 0.33, 90% interval 0.21 to 0.55. The upper end of that interval is the gene's LOEUF score, 0.55, which puts it in group 2 of 6, group 1 being the genes least tolerant of losing a copy. Missense variants: 320 observed, 514.77 expected, observed/expected ratio (o/e) 0.62, 90% interval 0.57 to 0.68. Synonymous variants: 194 observed, 185.56 expected, observed/expected ratio (o/e) 1.05, 90% interval 0.93 to 1.18.
Homologues: Orthologues: chimpanzee FBXL3 (100% identical), dog FBXL3 (99% identical), macaque FBXL3 (99% identical), pig FBXL3 (99% identical), guinea pig FBXL3 (98% identical), rabbit FBXL3 (98% identical), rat Fbxl3 (97% identical), mouse Fbxl3 (97% identical), zebrafish fbxl3a (85% identical), Drosophila melanogaster CG5003 (20% identical), Drosophila melanogaster CG8272 (18% identical), Drosophila melanogaster CG9003 (18% identical), and 23 more. Paralogues in human: FBXL13 (21% identical), FBXL20 (18% identical), FBXL18 (18% identical), FBXL2 (18% identical), FBXL6 (17% identical), FBXL5 (16% identical), FBXL7 (16% identical), FBXL4 (14% identical), FBXL16 (14% identical), SKP2 (14% identical), FBXL17 (13% identical), FBXL19 (12% identical), and 3 more.
Diseases named in the same sentence as FBXL3 in open-access papers:
FBXL3 is named in the same sentence as 17 diseases in open-access papers, as found by Europe PMC text mining. Sharing a sentence is not in itself a finding about the gene and the disease. The quoted sentences say what the papers report.
colorectal cancer (4 papers, 2017 to 2022). A primary or metastatic malignant neoplasm that affects the colon or rectum. "Moreover, miR-181d expression can also directly target the 3’-UTRs of CRY2 and FBXL3, providing information on its association with colorectal cancer." (PMID 30241461, 2018). "Recently, some studies found out that FBXL3 could also inhibit cell proliferation and migration in lung and colorectal cancer." (PMID 35197975, 2022). "A previous study demonstrated that miR-181d can act as an oncomiR that is upregulated in colorectal cancer (CRC) tissues and identified Fbxl3 as a direct target of miR-181d." (PMID 36553610, 2022).
Intellectual disability (2 papers, 2022 to 2024). "By exome sequencing, we have identified a FBXL3 mutation in patients with syndromic developmental delay accompanied by morphological abnormalities and intellectual disability, albeit with a normal sleep pattern." (PMID 35216494, 2022). "In family 13, five affected individuals were found to have a frameshift deletion mutation (c.885delT; p.Leu295Phefs25*) in FBXL3, which is associated with neurodevelopmental disorder with intellectual disability, short stature, facial anomalies, and speech defects (OMIM 606220)." (PMID 39281811, 2024). "These patients exhibit prenatal macrocephaly, midface hypoplasia, short stature, hypotonia and intellectual disability, similar to a recently reported case of three unrelated families bearing biallelic LOF variants of FBXL3." (PMID 35216494, 2022). "In the present study, we have identified a FBXL3 LOF mutation in a consanguineous family in which homozygous patients were affected with developmental delay, morphological abnormalities and moderate intellectual disability." (PMID 35216494, 2022).
bipolar disorder (1 paper, 2012). A disorder of the brain that causes unusual shifts in mood, energy, activity levels and the ability to carry out day-to-day tasks. "An analysis of three separate human data sets revealed a gene wide association between variation in FBXL3 and bipolar disorder (P = 0.009)." (PMID 22719873, 2012). "In order to translate findings from Afh mutants to human mania we investigated the association between variation in the human orthologue of Fbxl3 in three large genome-wide association studies of bipolar disorder and found evidence for association." (PMID 22719873, 2012). "Moreover, variation in the human orthologue of Fbxl3 was associated with bipolar disorder in three clinical samples." (PMID 22719873, 2012). "The current study therefore provides further evidence to an expanding literature linking circadian rhythm dysfunction and bipolar disorder and identifies FBXL3 as a potential candidate for study in human populations." (PMID 22719873, 2012).
colon cancer (1 paper, 2010). "Our genome-wide strategy to identify immunogenic NMD-resistant transcripts has identified five novel cMS mutations (SFRS12IP1, MED8, ASXL1, FBXL3, RGS12) in at least 45% of eleven MSI-High colon cancer cell lines tested." (PMID 21209843, 2010).
COVID-19 (1 paper, 2023). A disease caused by infection with severe acute respiratory syndrome coronavirus 2. "The gene FBXL3 has been identified as a core gene of COVID-19." (PMID 36913345, 2023).
developmental delay (1 paper, 2022). "Therefore, in humans, the most obvious phenotypes of the FBXL3 mutation are developmental delay and morphological abnormalities, while in the mouse model only disrupted circadian rhythms have been reported." (PMID 35216494, 2022).
lung adenocarcinoma (1 paper, 2023). A carcinoma that arises from the lung and is characterized by the presence of malignant glandular epithelial cells. "Survival analysis further revealed that CRY1, CRY2, GPER1, and FBXL3 were negatively related to survival of lung adenocarcinoma patients, while TIM were positively related to survival." (PMID 37924048, 2023).
muscle disorders (1 paper, 2025). "Additionally, exploring the translational potential of targeting FBXL3 in human muscle disorders, including sarcopenia and muscular dystrophies, will be essential for advancing therapeutic strategies." (PMID 40755783, 2025).
sarcopenia (1 paper, 2025). Progressive decline in muscle mass due to aging which results in decreased functional capacity of muscles. "Future studies should investigate the impact of FBXL3 modulation on muscle function and regeneration in aged animals and its interaction with other pathways implicated in sarcopenia, such as mitochondrial dysfunction and inflammation." (PMID 40755783, 2025). "Firstly, the study focuses on acute muscle injury models, and the long-term effects of FBXL3 modulation on muscle homeostasis and aging-related muscle decline, such as sarcopenia, remain to be explored." (PMID 40755783, 2025).
tumor (8 papers, 2020 to 2026). "Fbxl3 overexpression suppresses cell proliferation, stimulates cell apoptosis, arrests cell cycle, and prohibits cell invasion and migration efficiently, and has tumor inhibition prospects." (PMID 36553610, 2022). "Thus, FBXL3 is a remarkable molecular connection between circadian and cell cycle, and with tumor suppressive potentials." (PMID 32226545, 2020). "When Panther pathway analysis was performed separately for tumour suppressors and oncogenes, interestingly, biological process rhythmic process (GO:0048511) and pathway circadian clock system (P00015) were linked only to tumour-suppressor genes (CRY2 and FBXL3)." (PMID 34198662, 2021). "Immunohistochemical analysis of tumor tissues showed that MYC expression was downregulated after KDM4B knockdown, while FBXL3 and CRY2 expression was upregulated." (PMID 38093312, 2023). "Several F‐box containing proteins have been characterized either as tumor suppressors (FBXW8, FBXL3, FBXW8, FBXL3, FBXO1, FBXO4, and FBXO18) or as oncogenes (FBXO5, FBXO9, and SKP2)." (PMID 33822486, 2021). "Nearly ten years later, another unexpected regulatory function between FBXL3 and CRY2 is found that FBXL3 in cooperation with CRY2 targets an oncogenic substrate c-Myc to inhibit uncontrolled tumor cell growth." (PMID 32226545, 2020). "FBXL3 mediated degradation of CRY1 and CRY2 can re-activate the CLOCK-BMAL1 complex and increase the protein levels of period circadian protein homolog 1 (PER1) and 2 (PER2), two circadian clock regulators with tumor suppressor activity." (PMID 32226545, 2020). "In the tumor tissue, CRY1, TIM, and GPER1 expressions showed circadian rhythms in both the control and the TRF groups, but the circadian rhythm of TIM expression was more robust in the TRF group, while CRY2 were acyclic in the control group and FBXL3 were acyclic in the TRF group." (PMID 37924048, 2023).
cancer (7 papers, 2017 to 2026). A tumor composed of atypical neoplastic, often pleomorphic cells that invade other tissues. "Overexpression of Fbxo9 significantly reduced cancer cell migration compared with the overexpression of Fbxl3, Fbxl5, or Fbxl8." (PMID 38486234, 2024). "Several SRs, for example, members of the F-box protein family, such as Skp2, β-TrCP, Fbw7 and Fbxl3, were shown to play significant roles in cancer and other diseases." (PMID 28861005, 2017). "FBXL3 has been previously reported as an important cancer marker." (PMID 40313868, 2025). "Among 7912 samples across 18 cancer types, we interestingly observed that the majority of the clock control gene, such as HLF, KLF10, FBXL3, TEF, RORs (RORA, RORB, RORC), and NR1D2, are down-regulated in a wide range of cancers." (PMID 36895015, 2023). "In cooperation with FBXL3 (F-box and leucine rich repeat protein 3), CRY2 binds to MYC phosphorylated at threonine 58 and targets it for degradation, thus restricting proliferation in cancer cells." (PMID 28425940, 2017).
infection (1 paper, 2022). The state of being infected such as from the introduction of a foreign agent such as serum, vaccine, antigenic substance or organism. "Indeed, we identified several core circadian genes, such as Per2 and Fbxl3, differentially regulated at various time points of infection, suggesting a direct role for regulating these clock genes intrinsically in CD8+ T cells." (PMID 35944008, 2022).
FBXL3 also shares sentences with these, for which no sentence is quoted: lung carcinoma (2 papers); muscular dystrophies (1); neurodevelopmental disorder (1); Sepsis (1); Waardenburg syndrome type IV (1).